U2 (U2 spliceosomal RNA )
Synonyms: LOC124904140
Gene: Small nuclear RNA gene on chromosome 17 (43,271,369 to 43,271,559, reverse strand). Ensembl gene ENSG00000277903.
Gene Ontology:
Molecular function: pre-mRNA branch point binding
Biological process: mRNA branch site recognition
Cellular component: U2 snRNP
Homologues: Orthologues: chimpanzee U2 (100% identical), macaque U2 (100% identical), dog U2 (99% identical), pig U2 (48% identical), rat LOC120094029 (36% identical). Paralogues in human: U2 (100% identical), RNU2-2 (96% identical), U2 (95% identical), RNU2-3P (93% identical), RNU2-4P (93% identical), RNU2-17P (90% identical), RNU2-6P (90% identical), RNU2-48P (89% identical), RNU2-52P (89% identical), RNU2-59P (89% identical), RNU2-25P (87% identical), RNU2-26P (87% identical), and 68 more.